STUB1 (STIP1 homology and U-box containing protein 1)
Diseases named in the same sentence as STUB1 in open-access papers (continued):
Sharing a sentence is not in itself a finding about the gene and the disease.
tumor (continued). "Strikingly, compared to parental and control cells, tumour cells lacking Stub1 displayed significantly higher, IFNγ-dependent, MHC-I on cell surface." (PMID 35982220, 2022). "Despite these encouraging in vitro data and positive implications from clinical datasets, we did not observe in vivo benefits of inactivating Stub1 in mouse syngeneic tumour models—with or without combination with anti-PD-1 therapy." (PMID 35982220, 2022). "Mechanistic studies hint that SNPH is modified by the ubiquitin ligase CHIP/STUB1 and deubiquitinated in a USP7-dependant manner, which suggeststhat ubiquitination of SNPH isa pivotal regulator of mitochondrial trafficking and tumor cell invasion." (PMID 33498743, 2021). "Importantly, downregulation of STUB1 protein expression was correlated with tumor size and poor histological grade, not correlated with age and metastasis." (PMID 40651940, 2025). "The E3 ubiquitin ligase STUB1 (STIP1 homology and U-box containing protein 1) also polyubiquitinates PD-L1 in the cytoplasmic domain at lysine residues and downregulates PD-L1 expression, whereas CMTM6 maintains PD-L1 stability by blocking ubiquitination in tumor cells." (PMID 38762484, 2024). "However, we did not observe significant regression of Stub1-null tumours relative to the control tumours or improved median survival in the murine model." (PMID 35982220, 2022). "Importantly, loss of STUB1, but not PTPN2, increased the surface expression level of IFNGR1 in all three tumour lines, a result highly consistent with B16-F10 cells." (PMID 35982220, 2022). "However, unlike the control tumours, mice bearing the Stub1-null tumours responded to the anti-PD-1 treatment." (PMID 35982220, 2022). "However, we still cannot determine whether the regulation of TWIST1 expression by FAM64A through STUB1-mediated TWIST1 ubiquitination is the specific mechanism and whether there are other molecular mechanisms by which FAM64A inhibits OC tumor progression, which still needs further investigation." (PMID 40424038, 2025). "However, we observed no benefit by inactivating Stub1 in the transplanted tumour cells." (PMID 35982220, 2022).
neurodegenerative disease (20 papers, 2009 to 2025). A disorder of the central nervous system characterized by gradual and progressive loss of neural tissue and neurologic function. "On the other hand, a marked lowering of STUB1/CHIP levels has already been reported for aberrant autophagic fluxes in neurodegenerative disease, being associated with a parallel downregulation of Ser757 phosphorylated Ulk1." (PMID 39337505, 2024). "Our findings on four novel mutations in three novel STUB1 subjects extend the genetic spectrum of STUB1, corroborating earlier findings that STUB1 mutations both inside and outside of the tetratricopeptide repeat and U-Box domain of CHIP can lead to neurodegenerative disease." (PMID 28193273, 2017). "CHIP, the protein encoded by STUB1, is a central component of cellular protein homeostasis and interacts with several key proteins involved in the pathogenesis of manifold neurodegenerative diseases." (PMID 28193273, 2017). "This demonstrates that the recessive STUB1 mutations observed in our target cohort are not simply rare polymorphisms ubiquitous in neurodegenerative disease." (PMID 24742043, 2014). "No recessive STUB1 variants were identified in families with other neurological diseases, demonstrating that STUB1 variants are not simply rare polymorphisms ubiquitous in neurodegenerative disease." (PMID 24742043, 2014).
infection (13 papers, 2011 to 2025). The state of being infected such as from the introduction of a foreign agent such as serum, vaccine, antigenic substance or organism. "Knockdown of STUB1 expression inhibited the inhibitory effect of Sec10 on the transcriptional levels of Isg15, Isg54, and Isg56 triggered by infection with VSV or HSV-1." (PMID 40920886, 2025). "STUB1 overexpression also facilitates the inhibition of Bay41-4109 on the cccDNA formation in de novo infection of HBV." (PMID 35030230, 2022). "Infection of AdXbp1s in STUB1-Luc-transfected HEK293 cells resulted in concentration-dependent induction of luciferase activity." (PMID 33727534, 2021). "Immunoblot analysis demonstrated that the knockout of STUB1 blocked the Sec10-mediated degradation of STAT1 and inhibition of p-STAT1 upon infection with VSV or HSV-1." (PMID 40920886, 2025). "The results showed that RSV-L19 infection significantly increased ARCN1 and IKKε protein levels, whereas STUB1 expression remained unchanged." (PMID 41343552, 2025). "Consistently, Co-IP analysis showed that the interaction between endogenous STUB1 and IKKε was markedly reduced in ARCN1-knockdown RAW264.7 cells following 12 h of RSV-L19 infection (MOI = 10)." (PMID 41343552, 2025). "Furthermore, Co-IP and Western blot revealed a markedly enhanced interaction between ARCN1, STUB1, and IKKε in both RAW264.7 cells and PMs following RSV-L19 infection (MOI = 10) compared with uninfected controls." (PMID 41343552, 2025). "Further, the upregulation of TRADD and MLKL alongside the downregulation of the necroptosis inhibitor STUB1 suggests the priming, but not complete activation, of necroptosis in our in vitro infection model." (PMID 37795301, 2023).
neurological diseases (9 papers, 2014 to 2024). "To control for the specificity of STUB1 variants, we screened an additional 1707 exomes from 891 index families with other neurological diseases." (PMID 24742043, 2014). "STUB1 overexpression exerts neuroprotective functions in neurological diseases via modulating the degradation of some chaperone‐bound proteins." (PMID 34687132, 2021).
cardiovascular disease (8 papers, 2020 to 2025). "Recent studies have shown that Stub1 is involved in regulating various pathophysiological functions, including autophagy and lysosomal functions, aging, male reproduction, bone remodeling, neurodegeneration, and cardiovascular disorders." (PMID 39322015, 2024).
autosomal dominant disease (1 paper, 2022). Autosomal dominant form of disease. "SCA48, the most recently described SCA, is an autosomal dominant disease caused by mutation of the STIP1 homology and U box-containing 1 (STUB1) gene." (PMID 35398354, 2022).
kidney diseases (1 paper, 2021). "Our data indicated that STUB1 may protect against renal injury and act as a potential therapeutic target for kidney diseases." (PMID 34262937, 2021).
STUB1 also shares sentences with these, for which no sentence is quoted: colorectal cancer (11 papers); Parkinson disease (11); cerebellar ataxia (9); hematologic malignancies (9); ovarian carcinoma (9); acute myeloid leukemia (8); coronary artery disease (8); myeloid neoplasm (8); myocardial infarction (7); hematologic cancer (6); tauopathy (6); ischemic stroke (5); lymphoma (5); myelodysplastic syndrome (5); cardiomyopathy (4); colon carcinoma (4); gallbladder carcinoma (4); Huntington disease (4); renal carcinoma (4); acute kidney injury (3); cardiac diseases (3); cardiac ischemia (3); cognitive decline (3); COVID-19 (3); head and neck cancer (3); Insulin resistance (3); ischemia (3); lymph node metastasis (3); multiple myeloma (3); myeloproliferative neoplasm (3).
A further 131 diseases each share a sentence with STUB1 in 3 papers or fewer.